EGFR (epidermal growth factor receptor)
Diseases named in the same sentence as EGFR in open-access papers (continued):
Sharing a sentence is not in itself a finding about the gene and the disease.
glioblastoma (continued). "However, we chose to further examine the role of miR-221 as it displayed one of the highest probabilities of preferentially conserved targeting of EGFR and its expression significantly correlated with poor survival in Glioblastoma patients." (PMID 33082482, 2020). "Antibody-drug conjugates targeting EGFR may improve survival at the time of recurrence in EGFR-amplified glioblastoma." (PMID 32303258, 2020). "In particular, resistance to EGFR inhibition in human glioma cells was attributed to compensatory signaling by IGF-IR, and insulin receptor/IGF-IR signaling was shown to confer resistance to Gefitinib in EGFR-dependent glioblastoma, through compensatory AKT activation." (PMID 33072581, 2020). "This is particularly relevant for the connection between EGFR signalling in parental cancer cells and the induction of angiogenesis through dysregulated coagulation, a process which occurs also in glioblastomas, where it is initiated by EGFRvIII and proceeds though a TF feedback loop." (PMID 33302515, 2020). "However, glioblastoma heterogeneity of EGFR is further manifested by the wide variability in expression EGFRvIII." (PMID 33187135, 2020). "We hypothesized that miRNA-7 would able to sensitize glioblastoma cells to EGFR tyrosine kinase inhibitors (EGFR-TKIs) via the inhibition of EGFR." (PMID 32592373, 2020). "Among them, 19/43 (44%) were EGFR-amplified IDH-wt glioblastomas using FISH (19/43, 44%)." (PMID 32303258, 2020). "Here we explore whether EGFR expression is varied in matched treatment-sensitive and resistant glioblastoma cell lines." (PMID 33082482, 2020). "Interestingly, two EGFR-amplified glioblastomas, identified by dPCR and confirmed by FISH, had very low amount of DNA (2 ng and 6 ng)." (PMID 32303258, 2020). "In gliomas, the variant III of the epidermal growth factor receptor (EGFRvIII), which results from an in-frame intragenic deletion of EGFR exons 2–7, is present in approximately 20% to 30% of glioblastomas and a recognized target in many peptide vaccination studies." (PMID 32235752, 2020). "At first glance, it is surprising that targeting of EGFR has lagged in glioblastoma." (PMID 33187135, 2020). "There was also considerable interest in a Phase 3 trial using the antibody-drug conjugate depatuxizumab mafodotin (ABT-414), which binds activated EGFR, in combination with standard-of-care treatment in patients with newly diagnosed, EGFR-amplified glioblastoma." (PMID 33614476, 2020). "Interestingly, the remaining EGFR-amplified glioblastoma patient (patient #23) had 30% amplified cell nuclei and concordant copy number estimation by dPCR of 12.3 for EGFR1 and 14.5 for EGFR3." (PMID 32303258, 2020). "Because of EGFR’s role in the malignant process, elevated expression and accessibility on the tumor cell surface, EGFR-specific ITs represent highly potent immunotherapeutic agents across a wide range of diseases, including glioblastoma, breast, prostate and pancreatic cancer." (PMID 33014289, 2020). "Glioblastoma researchers have also targeted growth factor receptors such as EGFR and PDGFR using small-molecule tyrosine kinase inhibitors, monoclonal antibodies, and antibody drug conjugates, but these efforts have not yet translated into successful clinical trials." (PMID 33396284, 2020). "Despite the clear importance of the wt EGFR and EGFRvIII to glioblastoma progression, and a potential role for the EGFR in providing resistance to radiotherapy and chemotherapy, treatment with cetuximab, gefitinib, erlotinib or afatinib have all largely failed." (PMID 33082482, 2020).
glioblastoma (continued). "Hence, an EGFR-specific antibody (ZEGFR-03115) was conjugated to the photosensitizer IR700DX for glioblastoma treatments." (PMID 32194864, 2020). "Likewise, BGB324 in combination with an EGFR inhibitor has been shown to increase the mRNA expression of TIMP1 in glioblastoma cells." (PMID 31917795, 2020). "Moreover, it has also been recently confirmed that the proportion of patients with EGFR-amplified glioblastoma using NGS, FFPE-based or CGH-array techniques is between 35 and 45%." (PMID 32303258, 2020). "We investigated the effect of miR-200c on ZEB1 expression and cell migration in an in vitro transfection model with a miR-200c mimic, a miR-200c inhibitor and siRNA targeting EGFR in three short-term cultures with different levels of EGFR amplification obtained from resected glioblastomas." (PMID 33396457, 2020). "Efforts to target EGFR in glioblastoma continue to be investigated." (PMID 33187135, 2020). "We further confirmed upregulation of EGFR in 17 glioblastoma tissues compared to normal controls." (PMID 32962742, 2020). "In U87 glioblastoma cell line, β-catenin transactivation was found to be achieved via EGFR." (PMID 32714449, 2020). "In glioblastoma, EGFR-amplified tumors exhibit strong dependency on lipogenesis for growth." (PMID 32872164, 2020). "This study aimed to prospectively evaluate, on a long-term basis, corneal side effects secondary to compassionate administration of epidermal growth factor receptor (EGFR) inhibitor depatuxizumab mafodotin (ABT-414) in patients affected by EGFR-amplified recurrent glioblastoma." (PMID 33154952, 2020). "The aberrant EGFR-mediated oncogenic signaling is found in glioblastoma." (PMID 33117083, 2020). "In this study, for the first time, we explored whether EGFR signaling has an impact on the responses of differentiated GSCs to temozolomide, a drug of choice in glioblastoma therapy." (PMID 32788653, 2020). "Similarly, an inverse correlation between EGFR and miR-221 expression was observed in four primary cell lines generated from glioblastoma patient tumor tissue." (PMID 33082482, 2020). "Taken together, these data support that the detection of EGFR alterations may be considered relevant in patients treated for glioblastoma." (PMID 32303258, 2020). "This reduction in EGFR following TMZ and irradiation may assist in providing some explanation as to why targeting the EGFR in clinical trials of recurrent glioblastoma patients have largely failed." (PMID 33082482, 2020). "Moreover, N-glycosylation of SREBP cleavage-activating protein (SCAP) is essential for Golgi localization and activation of SREBP once EGFR induced glucose uptake in glioblastoma multiforme (GBM)." (PMID 33511116, 2020). "Furthermore, miR-137 promotes suppression of EGFR signaling in glioblastoma cells through direct targeting of EGFR." (PMID 32283739, 2020). "In the same year, Yu’s laboratory transduced human NK-92 cell line with a lentiviral construct that harbored a CAR targeting epidermal growth factor receptor (EGFR), which showed to be effective in the inhibition of glioblastoma growth and prolonged tumor-bearing mice survival." (PMID 33362790, 2020). "Targeting EGFR for glioblastoma treatment is an attractive therapeutic option." (PMID 31013819, 2019).
glioblastoma (continued). "This condition is present in approximately 50–60% of glioblastoma patients with EGFR amplification." (PMID 31013819, 2019). "Besides alterations of EGFR and EGFRvIII, loss of heterozygosity (LOH) is also a contributing factor in the progression of glioblastoma." (PMID 31013819, 2019). "However, glioblastomas are resistant to EGFR tyrosine kinase inhibitors (EGFR-TKIs), and overcoming resistance is essential." (PMID 31284441, 2019). "Amplification and rearrangement of the EGFR gene have frequently been reported in glioblastoma." (PMID 31013819, 2019). "Such tumors are usuallyaggressive and similar to primary glioblastomas in their molecularcharacteristics (aberrations in EGFR, PTEN, NF1, CDKN2A/B).The third group, for which the prognosis turned out to be intermediate betweenthe two, includes mutIDH in the absence of 1p/19q codeletion." (PMID 31413876, 2019). "Hence, we investigated four glioblastoma cell lines in a pilot study to identify a cell line with an adjustable EGFR-signaling pathway." (PMID 31438847, 2019). "We found that cytokine release and target cell killing by the EGFR806-CAR were similarly effective in all glioblastoma cell lines tested, and that it was active against EGFRvIII-transduced fetal human astrocytes, which expressed approximately 3000-4000 EGFR copies per cell." (PMID 31903167, 2019). "Alternatively, inhibition of EGFR by erlotinib in EGFRvIII-expressing U87 glioblastoma cells may increase the expression of PDGFRβ, which compensates for signaling inhibited by erlotinib." (PMID 31284441, 2019). "A mouse model of glioblastoma demonstrated EGFR protooncogenic interplay supporting PTEN deletion." (PMID 31661771, 2019). "Epidermal growth factor receptor (EGFR) is a well-established therapeutic target in glioblastoma." (PMID 31798595, 2019). "Currently, a range of epigenetic drugs including histone deacetylase (HDAC) inhibitors, DNA methylation and histone inhibitors, microRNA, and different types of EGFR inhibitor molecules are being actively investigated in glioblastoma patients as therapeutic strategies." (PMID 31013819, 2019). "Thus, in this glioblastoma patient, prominent phenotypic and genotypic changes, most notably the elimination of EGFR-amplified tumour cells, occurred after targeted treatment with an EGFR tyrosine kinase inhibitor." (PMID 30644426, 2019). "Adding the EGFR TKI erlotinib to vorinostat is an effective strategy to treat glioblastoma cells." (PMID 31013819, 2019). "Therein, glioblastoma with a constitutively activated ERK, e.g., the glioblastoma characterized by EGFR/PDGFR amplification or oncogenic mutations, may result as both resistant to targeted-therapy and immune-resistant." (PMID 31117237, 2019). "However, the results of clinical trials with first- and second-generation EGFR-TKIs for glioblastoma were disappointing." (PMID 31284441, 2019). "However, approximately 70–90% of primary glioblastomas with EGFR overexpression demonstrated EGFR amplification." (PMID 31013819, 2019). "Many previous studies observed the overexpression of EGFR in primary glioblastoma." (PMID 31013819, 2019). "Signal transduction via EGFR plays an essential role in glioblastoma." (PMID 31617054, 2019). "Exosomes isolated from the serum of glioblastoma patients show increased levels of glioblastoma-specific epidermal growth factor receptor (EGFR) vIII, suggesting that it could be used as a diagnostic marker for cancer." (PMID 30987213, 2019). "Its overexpression has been shown to be associated with enhanced metastatic potential in glioblastoma, with EGFR at the top of a downstream signaling cascade that controls basic functional properties of glioblastoma cells such as survival, cell proliferation, and migration." (PMID 31013819, 2019).
glioblastoma (continued). "Furthermore, EGCG has been reported to inhibit epidermal growth factor (EGF)-induced activation of the EGF-receptor (EGFR), a frequently encountered aberrant oncogenic pathway in glioblastoma and many other cancers." (PMID 31139406, 2019). "To date, many antibodies have been developed against EGFR to treat glioblastoma patients." (PMID 31013819, 2019). "Of note, inhibition of EGFR induces a MET-driven stem cell population in glioblastoma." (PMID 31221203, 2019). "The authors further observed that all of the primary glioblastomas showed EGFR overexpression." (PMID 31013819, 2019). "EGFR-tyrosine kinase inhibitors (TKIs) and neutralizing antibody (EGFR monoclonal antibodies) treatments can induce autophagy in multiple cancers, including glioblastoma, human vulvar squamous carcinoma, colorectal adenocarcinoma, and NSCLC cells." (PMID 31527477, 2019). "Furthermore, since the safety profile of osimertinib was found to be better than those of other standard EGFR-TKIs in clinical trials, it is one of the promising drugs for the treatment of pancreatic cancer and glioblastoma." (PMID 31614999, 2019). "Approximately 40% of glioblastoma multiforme (GBM) patients have tumors that overexpress EGFR." (PMID 30601871, 2019). "In addition, U87.MG wild-type cells and their counterpart glioblastoma cells transfected with a deletion-activated EGFR cDNA (U87.MG.ΔEGFR) were investigated." (PMID 31164821, 2019). "Enhanced EGFR abundance and signaling in glioblastoma can occur by different mechanisms, such as alterations in genetic information (amplification of receptor, mutation, and chromosomal translocation), angiogenesis, autocrine and paracrine signaling, and epithelial–mesenchymal transition." (PMID 31013819, 2019). "Here we present a case of recurrent glioblastoma in which EGFR gene amplification present in the pre-treatment tumour subsequently disappeared in the tumour that progressed on targeted treatment with the EGFR tyrosine kinase inhibitor dacomitinib." (PMID 30644426, 2019). "The mechanisms of resistance to EGFR-TKI in glioblastomas remain obscure." (PMID 31284441, 2019). "However, the development of resistance against EGFR inhibitors in glioblastoma patients stimulated the development of multitargeted drugs or epigenetic drugs or the use of a combination of drugs for glioblastoma treatment." (PMID 31013819, 2019). "The poor response of EGFR-targeted therapies raises the question of whether EGFR alterations truly represent key drivers in the genesis of glioblastomas." (PMID 31073965, 2019). "In glioblastoma cells the regulations upon EGFR inhibition differ." (PMID 30360441, 2018). "Mutations affecting EGFR gene result in its overexpression in 30–50% of glioblastoma, 25–82% in colorectal cancer and 5–20% in non-small-cell lung cancer." (PMID 29455662, 2018). "In contrast, when EGFR mutations were observed in low-grade gliomas, they were associated poor outcomes, but EGFR mutations were non-prognostic in high-grade glioblastomas." (PMID 30526857, 2018). "EGFR drives robust upregulation of tissue factor (TF) in tumor cells derived from glioblastoma." (PMID 30093972, 2018). "The same interaction might be the reason for the anti-EGFR-therapy resistance of glioblastoma cells." (PMID 30360441, 2018). "We hypothesize that fluorescently labeled antibodies against EGFR will allow for sensitive and specific tumor detection in real-time and can be used safely for the targeted intraoperative detection of primary glioblastoma." (PMID 29623552, 2018). "The possible role of EGFRvIII in glioblastoma cancer stem cells is also supported by the observation that the induction of differentiation of glioblastoma stem-like cells leads to downregulation of EGFR and EGFRvIII and decreased tumorigenic and stem-like potential." (PMID 30279357, 2018). "In the classical subtype of glioblastoma hyperexpression of EGFR was frequently observed." (PMID 30279357, 2018).
glioblastoma (continued). "Honokiol also Inhibits glioma/glioblastoma progression by targeting EGFR." (PMID 30587839, 2018). "Our data show that DSE regulates EGFR/ErbB2 signaling, and DSE expression may be positively associated with ErbB2 levels in glioblastoma cells." (PMID 29864158, 2018). "It was suggested that the heterogeneous expression of the EGFRvIII mutant could contribute to mediate the resistance of glioblastoma cells to EGFR inhibitors." (PMID 30279357, 2018). "Interestingly, the inhibition of EGFR with TKIs in glioblastoma cells leads to completely unexpected regulations in the MAPK-related interactome of PTPIP51." (PMID 30360441, 2018). "Even though there have been attempts to develop targeted therapies for glioblastoma, such as EGFR and VEGFR inhibitors erlotinib and tivozanib, to date there is no effective treatment for this cancer and development of drug resistance is one of the major problems with current therapies." (PMID 30329087, 2018). "Consistent with this hypothesis, blockade of mTOR signaling by inhibitors of mTOR or EGFR promote nuclear PML expression in glioblastoma cells." (PMID 30374421, 2018). "However, based on published analysis of primary glioblastoma tumor samples and clinical information, we anticipate that the level of expression of antigens (e.g., EGFR) on the EV surface will be far more heterogeneous than our EVs generated from cell cultures." (PMID 29330365, 2018). "To determine whether activated EGFR signaling affects glioblastoma neurosphere formation, we prepared neurospheres with U87 and U87vIII cells under equivalent conditions." (PMID 29445239, 2018). "Although the mechanisms underlying the regulation of ErbB2 expression by DSE require further investigation, our inhibitor experiments suggest that EGFR/ErbB2 signaling could involve in the development of DSE-mediated malignant phenotypes in glioblastoma cells." (PMID 29864158, 2018). "Moreover, it is known that EGF plays a role in the metastasis of glioblastoma by induction of matrix metalloproteinase-9 in an EGFR-dependent mechanism." (PMID 29584702, 2018). "In our previous study, we immunized mice with EGFR-expressed glioblastoma cells or purified recombinant EGFR to produce EMab-134 clone (IgG1, kappa), which reacted with endogenous EGFR of oral cancers in flow cytometry, Western blotting, and immunohistochemistry." (PMID 29872734, 2018). "Therefore, IGFBP2, EGFR_pY1068, HER2_pY1248, and EGFR_pY1173 are affected in the same way by IDH1 mutations in low-grade glioma and glioblastoma, and we report a cross-cancer effect for those groups." (PMID 30442178, 2018). "Additional studies have supported heterogeneity of EGFR in glioblastoma development." (PMID 30279357, 2018). "Among all these cancer types, glioblastoma has the highest rate of EGFR gene alteration." (PMID 30016965, 2018). "However, multiple attempts to inhibit this pathway in glioblastoma using EGFR tyrosine-kinase inhibitors (TKIs) and naked monoclonal antibodies (mAbs) have not been successful." (PMID 29615902, 2018). "Thus, uPAR functions as a major regulator of glioblastoma subtype in neurosphere culture even when EGFR signaling is constitutively activated." (PMID 29445239, 2018).